MMP9 (matrix metallopeptidase 9)
Diseases named in the same sentence as MMP9 in open-access papers (continued):
Sharing a sentence is not in itself a finding about the gene and the disease.
brain arteriovenous malformations (4 papers, 2005 to 2025). "The primary aim of this study is to demonstrate the feasibility of utilizing doxycycline to suppress matrix metalloproteinase-9 (MMP-9) in brain arteriovenous malformations (AVMs)." (PMID 15667660, 2005). "Immunohistochemistry showed higher levels of total MMP-9, active MMP-9, pro-MMP-9, and tissue inhibitors of metalloproteinases (TIMP)-1 and TIMP-3 in the brain arteriovenous malformations (AVM) specimen than in the control samples." (PMID 25932641, 2015).
Brain atrophy (4 papers, 2016 to 2025). Partial or complete wasting (loss) of brain tissue that was once present. "The CHI3L1 (chitinase-3-like protein 1) level in the CSF was strongly correlated with brain atrophy, and the CSF levels of CXCL1, MMP-9, CCL22, CXCL13, and CXCL10 were correlated with the development of new lesions in T2 MRI." (PMID 34602928, 2021).
brain cancer (4 papers, 2015 to 2023). A primary or metastatic malignant neoplasm affecting the brain. "Among these, MMP9 expression is the most relevant for positive correlation with brain cancer progression." (PMID 36048342, 2022).
cervical squamous cell carcinoma (4 papers, 2014 to 2024). A squamous cell carcinoma arising from the cervical epithelium. "The increased MMP-9 expression makes the main contribution to the invasive potential of squamous cell cervical carcinomas." (PMID 24476461, 2014).
chordoma (4 papers, 2021 to 2026). Chordomas are rare malignant tumors arising from embryonic remnants of the notochord in axial skeleton. "In all four chordoma cell lines, changes in expression were most distinct for MMP9." (PMID 34127734, 2021). "Specifically, chordomas have been reported to express elevated levels of VEGF and MMP-9." (PMID 40026939, 2025). "Despite the identification of numerous genes with dysregulated expression in vitro or in vivo in chordoma (e.g. brachyury, EGFR, Ezrin, MMP-9, c-MET, FHIT, etc.) conventional or targeted chemotherapeutic agents showed a partial response at best-case scenarios in clinical case-series." (PMID 36033338, 2022).
choroidal neovascularization (4 papers, 2016 to 2025). An eye disorder described by the growth of new blood vessels that originate from the choroid through a break in the Bruch membrane into the sub–retinal pigment epithelium (sub-RPE) or subretinal space. "C18PGM was selectively cleaved by MMP-9, releasing minocycline and inhibiting MMP-9 expression in a laser-induced choroidal neovascularization (CNV) mouse model, suppressing choroidal inflammation and neovascularization." (PMID 40284474, 2025). "Absence of MMP-2 and MMP-9 inhibits experimental choroidal neovascularization." (PMID 26872030, 2016).
chronic hepatitis C (4 papers, 2016 to 2024). "Similarly, the quantities of LCN2 in fresh spot urine samples were found to correlate with fibrosis score and reflected the increased activity of matrix metalloproteinase-9 (MMP-9) in urine in patients suffering from chronic hepatic C infection." (PMID 27729871, 2016).
coronary aneurysm (4 papers, 2016 to 2022). Abnormal balloon- or sac-like dilatation in the wall of coronary vessels. "These, together with high levels of MMP-9 that can break down elastin in coronary artery walls, promote the development of coronary aneurysms during the pathogenic process of KD." (PMID 27800490, 2016).
deafness (4 papers, 2022 to 2024). An inherited or acquired condition characterized by the complete loss of the ability to hear from one or both ears. "Among the overlapped DEGs and ASGs, we found two and one hearing loss/deafness genes in R. affinis himalayanus (MMP9 and MPO) and R. sinicus (TPM2), respectively." (PMID 38672325, 2024). "It is known that one of the molecules involved in neuronal connectivity after deafness treatment is matrix metalloproteinase-9 (MMP-9)." (PMID 36835126, 2023). "In the subgroup with DFNB1-related deafness, whohad CI activation after 1 year old (N = 22), amultiple regression model showed that rs3918242 of MMP9 was a significant predictor of overall LEAQ score atfollow-up." (PMID 35061219, 2022). "Out of the tested genetic variants of MMP9 and BDNF, only rs3918242MMP9 showed significant association withauditory development in the subgroup with DFNB1-related deafness." (PMID 35061219, 2022). "Nevertheless, the regulation of MMP-9 is complex and the exact mechanisms by which MMP-9 affects the processes of memory and language formation following deafness treatment remain unknown." (PMID 37004521, 2023). "Our findings that MMP-9 and BDNF plasma levels play an important role in governing auditory development following deafness treatment are necessarily tentative and require verification." (PMID 36835126, 2023).
diverticulitis (4 papers, 2016 to 2024). An infection that develops in the diverticula of the intestinal tract. "This collective elevation in MMP-3 and MMP-9 activity potentially engenders an escalated degradation of basal lamina proteins, thereby establishing a plausible predisposition to colonic diverticulosis." (PMID 38004080, 2023). "Given this intricate relationship between MMPs and colonic diverticulosis, this pilot study sought to investigate whether selected genetic variants in MMP3, MMP9, and MMP12 are associated with the incidence of colonic diverticulosis." (PMID 38004080, 2023). "Whilst a collagen deficit does not identify individuals who will go on to develop diverticulitis, one study demonstrated downregulation of MMP2, MMP9 and MMP13 expression and an increase in MMP1, TIMP1 and TIMP3 in inflamed mucosa of patients with diverticulitis versus Crohn’s disease." (PMID 38831715, 2024).
ductal carcinoma in situ (4 papers, 2016 to 2024). "This showed uniformly weak MMP9 expression in normal glandular epithelium and ductal carcinoma in situ (DCIS)." (PMID 32445177, 2020).
endometrial polyp (4 papers, 2017 to 2025). A benign nodular lesion protruding above the surface of the endometrium. "Additionally, CD138-positive cell infiltration has been shown to associate with endometrial polyps and alterations in molecular markers such as TGF-β1, MMP-9, and αvβ3 integrin, which are associated with endometrial dysfunction and prolonged inflammation." (PMID 40539061, 2025).
endometrioid carcinoma (4 papers, 2011 to 2023). "Interestingly, in the analysis by histological subtypes, AR is mainly associated to MMP-2 in HGSC and significantly associated to MMP-9 in endometrioid carcinoma." (PMID 32718331, 2020). "Meanwhile, a significant association was observed between AR and MMP-9 in endometrioid carcinoma." (PMID 32718331, 2020). "A significantly higher percentage of slides expressed MMP-9 with a low immunoreactivity in grade 1 (90%) but not in grade 2 (71.4%) and grade 3 (66.7%) endometrioid carcinoma when compared with atrophic endometrium (20%) (p < 0.05)." (PMID 36945954, 2023). "The secretory endometrium also showed a significantly higher percentage of nonstaining with MMP-9 (36.4%) compared to grade 1 and 2 endometrioid carcinomas (0%) (p < 0.05)." (PMID 36945954, 2023). "On the contrary, in HGSC and endometrioid carcinoma the frequency of MMP-2 in stroma is almost reduced by half, probably in relation to the malignancy of both subtypes, although this particular distribution is not observed for MMP-9." (PMID 32718331, 2020).
eosinophilia (4 papers, 2007 to 2023). "Certain studies have indicated that the upregulation of MMP9 may be associated with eosinophilia." (PMID 25187823, 2014). "In contrast to a marked peribronchial tissue eosinophilia, eosinophils in the airway were remarkably reduced in both MMP-2 and MMP-9-deficient mice." (PMID 25090641, 2014). "Eosinophilia in curcumin-treated mice was markedly reduced, co-stimulatory molecule expression (CD80, CD86, and OX40L) on antigen-presenting cells was decreased, and expression of MMP-9, OAT, and TSLP genes was also attenuated." (PMID 17254346, 2007).
Fever (4 papers, 2021 to 2024). Body temperature elevated above the normal range. "Importantly, MPO, MMP9 and PRTN3 levels in the placenta associate with self-reported fever in this cohort of parturient women." (PMID 34737733, 2021). "The concentration of MMP-2, MMP-3, MMP-9, MMP-13, TIMP-1, and FG-α in the KD group were significantly higher than those in the fever group (p < 0.05).The KD group was divided into two subgroups, patients with combined CAL and 179 patients without combined CAL." (PMID 37575991, 2023). "The concentration of MMP-2, MMP-3, MMP-9, MMP-13, TIMP-1, and FG-α in the KD group were significantly higher than those in the fever group (p < 0.05)." (PMID 37575991, 2023). "The results demonstrated that the levels of ET-1, ICAM-1, TNF-α, IL-1β, MMP-9, NF-κB, NO, and TXB2 in yeast-induced fever in the model group rats were significantly higher than in the control group (P < 0.001)." (PMID 35178159, 2022).
fungal infection (4 papers, 2018 to 2025). "The significance of hub genes, specifically IL-1B, MMP9, and S100 family members, in promoting inflammatory and immunological responses during fungal infections is highlighted by this investigation." (PMID 40521031, 2025). "For the control group, it was evident that the expression of both TNF-α and MMP-9 increased significantly in the stromal layer during the course of the fungal infection." (PMID 29403058, 2018).
Guillain-Barre syndrome (4 papers, 2011 to 2025). A spectrum of rare post-infectious neuropathies that usually occur in otherwise healthy patients. "Higher plasma MMP-9 levels were associated with demyelination and peripheral nerve dysfunction in Guillain-Barré syndrome." (PMID 41245602, 2025). "In patients with Guillain-Barré syndrome, the expression of MMP-9 and pro-inflammatory cytokines decreases in the recovery stage." (PMID 37206663, 2023). "In a recent study on experimental chicken model, enhanced production of MMP-9 correlated with pathology in C. jejuni-induced Guillain-Barré syndrome." (PMID 30551610, 2018). "The detection of active matrix metalloproteinase-9 (MMP-9) by ELISA (enzyme-linked immunosorbent assay) in serum from patients with ALS and Guillain-Barre syndrome and its correlation with nerve damage suggests that MMP-9 can be used as an early marker in both disorders." (PMID 21826267, 2011).
hemangioma (4 papers, 2015 to 2025). A benign vascular lesion characterized by the formation of capillary-sized or cavernous vascular channels. "In vascular endothelial cells, propranolol is considered to induce vascular contraction by suppressing NO production, inhibit renin production, control angiogenesis by regulating the expression of VEGF•bFGF•MMP2/MMP9, and induce apoptosis, but it may also affect pericytes and hemangioma stem cells." (PMID 32202048, 2020). "Hypoxia-induced factors important for postnatal vasculogenesis (SDF-1α, MMP-9, VEGF-A, HIF-1α) are upregulated in children with proliferating hemangiomas." (PMID 39997620, 2025).
HIV-1 infection (4 papers, 2010 to 2022). The type species of lentivirus and the etiologic agent of acquired immunodeficiency syndrome (AIDS). "Altered levels of MMP-9 have been reported to correlate with HIV-1 infection, and breakdown of extracellular matrix has been suggested to aid dissemination of the virus." (PMID 20463814, 2010). "The second study assessed the neuroinflammatory effect of HIV-1 infection in brain tissue, which was characterized by its sudden onset and increase in activity and expression of MMP-2 and MMP-9." (PMID 35743229, 2022). "While a limitation of the study were the small number of cases, the study demonstrates that maternal HIV-1 infection might not have a dramatic influence on placental IGF1, IGFBP1, MMP2, MMP9, ANG1, ANG2 and Gal-13 levels in Cameroonian pregnant normotensive women with majority receiving cART." (PMID 31042729, 2019).
hypertrophic cardiomyopathy (4 papers, 2016 to 2025). A condition in which the myocardium is hypertrophied without an obvious cause. "In patients with familial hypertrophic cardiomyopathy (HCM) an association of MMP-9 with gadolinium enhancement in cardiac MRI was recently described and an important role of the MMP system in cardiac remodeling and fibrosis was proposed." (PMID 30159316, 2018).
hyperuricemia (4 papers, 2017 to 2023). An abnormally high level of uric acid. "The mice in the hyperuricemia + Ang II group showed increased levels of MMP-9 (9.04-fold, n = 6, P < 0.05), URAT1 (6.8-fold, n = 6, P < 0.05), and p-ERK1/2 (8.19-fold, n = 6, P < 0.05)." (PMID 36710339, 2023). "Furthermore, the induction of hyperuricemia alone enhanced the abundance of MMP-9, URAT1, and p-ERK1/2 expression in the abdominal aorta in ApoE-KO mice compared with control mice (2.37-fold, n = 6, P < 0.05; 1.92-fold, n = 6, P < 0.05; and 2.51-fold, n = 6, P < 0.05)." (PMID 36710339, 2023). "Mice with hyperuricemia presented higher protein levels of URAT1, p-ERK1/2 and MMP-9 in aortic tissue than mice with normal serum uric acid levels." (PMID 36710339, 2023). "In our study, mice with hyperuricemia alone that were not treated with Ang II presented increased aortic diameters, exacerbated elastin degradation, and elevated MMP-9 protein levels." (PMID 36710339, 2023). "In addition, our murine experimental evidence suggests that hyperuricemia exacerbates AAA formation and reveals that the URAT1/ERK1/2/ROS/MMP-9 pathway is among the pathways activated by uric acid in HASMCs." (PMID 36710339, 2023). "Interestingly, our data showed an elevated-MMP-9 level and a decreased-MMP-7 level in hyperuricemia mouse." (PMID 28445133, 2017).
Hypoglycemia (4 papers, 2021 to 2025). A decreased concentration of glucose in the blood. "It is suggested that severe hypoglycemia in the high-glucose state can cause increased MMP9 expression in brain pericytes, which further causes degradation of the TJ proteins and leads to BBB disruption." (PMID 34899278, 2021). "Multiple factors are involved in the development of hypoglycemia-induced brain injury, such as oxidative stress, heightened production of reactive oxygen species, elevated levels of inflammatory factors like TNF-α and IL-6, and the activation of MMP9." (PMID 39004753, 2024).
intestinal inflammation (4 papers, 2016 to 2019). "In a study on childhood gastroenteritis, two Campylobacter and four Salmonella patients were included and showed elevated serum concentrations of MMP-9 and TIMP-1 as compared to healthy controls." (PMID 30551610, 2018).
intrahepatic cholangiocarcinoma (4 papers, 2019 to 2025). A carcinoma that arises from the intrahepatic bile duct epithelium in any site of the intrahepatic biliary tree. "MMP-9 was first recognized as a prognostic factor related to LNM in intrahepatic cholangiocarcinoma (ICC) in 1999, with a higher expression indicating a higher risk of recurrence." (PMID 40564091, 2025).
intraventricular haemorrhage (4 papers, 2018 to 2026). "In very immature preterm infants, increased local and systemic expression of MMP-9 has also been associated with intraventricular hemorrhage, white matter brain injury and retinopathy of prematurity." (PMID 29558521, 2018). "The objective of the present study is to examine the association between the presence of various forms of matrix metalloproteinase genes (MMP-1, MMP-9, TIMP-1 and TIMP-2) and their tissue inhibitors, and the incidence of intraventricular haemorrhage (IVH) in premature neonates." (PMID 41898459, 2026).
invasive carcinoma (4 papers, 2008 to 2024). A carcinoma that is not confined to the epithelium, and has spread to the surrounding stroma. "Upregulation of MMP-2 and MMP-9 expression and activity are the most common extracellular matrix-related modifications in precursor cervical lesions and invasive carcinoma." (PMID 38612895, 2024). "It is noteworthy that women with sclerosing adenosis exhibited significantly elevated MMP-9 expression, similar to that observed for invasive carcinoma." (PMID 19889214, 2009). "In HCC MMP9 expression and activity is predictive of metastatic and invasive carcinoma." (PMID 30513115, 2018). "In particular, MMP9 and MMP2 (also know as gelatinases) are involved in the degradation of type 4 collagen that comprises basement membranes, a process thought to be important in the development of invasive carcinoma and metastasis." (PMID 18954444, 2008). "In particular, MMP9 and MMP2 are involved in the degradation of type 4 collagen, which comprises basement membranes, a process thought to be important in the development of invasive carcinoma and metastasis." (PMID 18954444, 2008).
juvenile idiopathic arthritis (4 papers, 2006 to 2022). Juvenile idiopathic arthritis (JIA) is the term used to describe a group of inflammatory articular disorders of unknown cause that begin before the age of 16 and last over 6 weeks. "The use of etanercept, a TNF inhibitor, has been shown to reduce MMP-9 levels in children with polyarticular juvenile idiopathic arthritis, corroborating the role of TNF in MMP-9 production." (PMID 36311773, 2022). "In the aqueous humor of juvenile idiopathic arthritis patients with anterior uveitis, the levels of MMPs (MMP1, MMP3, MMP9) are significantly higher than those in controls." (PMID 35274006, 2022). "The aim of this study was to evaluate the concentration of MMP-2, MMP-8, and MMP-9 and their inhibitors TIMP-1 and TIMP-2 of unstimulated whole saliva (UWS) in correlation with the oral health in juvenile idiopathic arthritis (JIA) children." (PMID 31781639, 2019).
leprosy (4 papers, 2018 to 2024). Leprosy is a chronic infectious disease affecting primarily the skin and peripheral nervous system. "As a final point, MMP9 serum analyses in conjunction with morphological observations lead to degranulation as the source of LDNs in leprosy." (PMID 34692720, 2021). "In patients with leprosy presenting with inflammatory reversal reactions and erythema nodosum leprosum (ENL), the levels of MMP9 in tissue and circulation were elevated." (PMID 39602398, 2024). "Increased MMP-2, MMP-9 mRNA, and protein MMP-9 levels were detected together with enhanced TNF-α and IFN-γ expression levels in the lesions of both tuberculoid patients and in those undergoing leprosy reactions like ENL." (PMID 34692720, 2021).
liver failure (4 papers, 2016 to 2024). A liver disease characterized by the liver losing or has lost all of its function. "MMP-9 is a member of a family of zinc-dependent neutral proteases that degrade the extracellular matrix and basement membrane and has been implicated in sinusoidal injury in liver failure, liver remodelling and necrosis." (PMID 34813621, 2021). "For instance, blood levels for matrix metalloproteinase 9 (MMP9) are increased following hepatic failure and MMP9 blocking with a monoclonal antibody can protect the BCB6." (PMID 38310100, 2024).
membranous nephropathy (4 papers, 2020 to 2025). "In a rat model of membranous nephropathy, a correlation between increased expression of MMP-9 within the visceral epithelial cells and the proteinuria was reported." (PMID 32655553, 2020).
meningoencephalitis (4 papers, 2019 to 2024). Inflammation of the meninges and brain, generally secondary to an infectious cause. "Indeed, a single nucleotide polymorphism in the MMP9 gene, rs17576, was found to be significantly higher in patients with meningoencephalitis than those with meningitis (p = 0.042)." (PMID 37959323, 2023). "The BBB permeability is enhanced in mice with eosinophilic meningitis or meningoencephalitis, which may be caused by MMP-9 or MMP-12." (PMID 31415587, 2019). "The expression of the Cav-1 protein is positively correlated with brain edema, BBB permeability, and MMP-9 activity in infection-induced meningoencephalitis with A. cantonensis." (PMID 38922036, 2024). "In TBE patients, the presence of detectable serum matrix metalloproteinase 9 (MMP 9) has been observed to predict meningoencephalitis development." (PMID 37959323, 2023).